ZNF671 (zinc finger protein 671)
Diseases named in the same sentence as ZNF671 in open-access papers (continued):
Sharing a sentence is not in itself a finding about the gene and the disease.
tumor (continued). "Having demonstrated that ZNF671 is epigenetically silenced by DNA methylation, we then investigated a possible tumor suppressive role of ZNF671 in bladder UC cells." (PMID 26320192, 2015). "ZNF671 expression was significantly down-regulated in five tumor tissue samples as compared to their adjacent normal counterparts." (PMID 26320192, 2015). "We first confirmed the microarray result by bisulphite pyrosequencing that showed a linear correlation between β-values (from the array) and DNA methylation levels of the promoter region of ZNF671 in the same tumor tissue samples." (PMID 26320192, 2015). "Taken together, these in vitro and in vivo results strongly suggest ZNF671 to be a potential tumor suppressor in advanced human bladder UC." (PMID 26320192, 2015). "In this study, we found that ZNF671 was epigenetically silenced by promoter hypermethylation in UC cell lines and patient tumor tissue samples." (PMID 26320192, 2015). "ZNF671 re-expression in UC cell lines, via ectopic expression, inhibited tumor growth and invasion, in possible conjunction with downregulation of cancer stem cell markers (c-KIT, NANOG, OCT4)." (PMID 26320192, 2015). "Nude mice subcutaneously injected with ZNF671-overexpressing UMUC3 cells grew tumors of significantly less tumor volume and weight, as compared to mice injected with UMUC3 cells stably transfected with the empty vector control." (PMID 26320192, 2015). "The correlation between UC tumor tissue ZNF671 hypermethylation and locoregional disease-free survival was also analyzed." (PMID 26320192, 2015). "Given the established role of Notch signaling in immune regulation, it is plausible that ZNF671 may modulate the tumor immune microenvironment through this pathway." (PMID 40791581, 2025). "In summary, both ZNF132 and ZNF671 may play crucial roles in regulating immune responses and tumor-stroma interactions." (PMID 40791581, 2025). "However, migration of UM-SCC-1 cells, measured using the Radius 96-well cell migration assay, showed that expression of ZNF671 resulted in a significant decrease in tumor cell migration when compared to the empty vector control cells." (PMID 39595048, 2024). "While EDNRB and FMN2 as well as TBXT and ZNF671 could have potential tumor suppressor functions, MOS is a well-known oncogene." (PMID 38643219, 2024). "Similarly, overexpression of ZNF671 resulted in a significant decrease in tumor cell invasion compared to the empty vector control cells as measured by trans-well invasion assay." (PMID 39595048, 2024). "In vivo experiments confirmed that overexpression of ZNF671 inhibited tumor growth." (PMID 37215982, 2023). "In addition, we also found that MAPK6 was highly expressed in tumor tissues, especially in the low ZNF671 group." (PMID 37215982, 2023). "In addition, through correlation analysis, it was found that the low expression level of ZNF671 was closely related to the prognosis of tumor patients, that is, tumor patients with low expression level of ZNF671 had a poorer prognosis." (PMID 37215982, 2023). "ZNF671, also located on Chromosome 19, might play a tumor suppressor role in cancer since it was found downregulated in eight cancer-related ZNF671 single-cell RNA-Seq datasets." (PMID 32796700, 2020). "CCK-8 and Transwell functional assays showed that ZNF671 could inhibit tumor cell proliferation, migration, and invasion." (PMID 31134149, 2019). "CCK-8 and Transwell migration and invasion assays showed that ZNF671 could inhibit tumor cell proliferation, migration, and invasion." (PMID 31134149, 2019). "ScRNA-seq functional state analysis showed that ZNF671 played a tumor suppressor role and/or an oncogenic role in angiogenesis, apoptosis, cell cycle, differentiation, DNA damage, DNA repair, EMT, hypoxia, inflammation, invasion, metastasis, proliferation, quiescence, and stemness." (PMID 31781507, 2019). "The potential tumor suppressor ZNF671 is epigenetically silenced by promoter methylation in NPC." (PMID 29052525, 2017).
tumor (continued). "Taken together, these results support the postulate that ZNF671 could inhibit tumor growth and invasion through down-regulation of determinants of dedifferentiation." (PMID 26320192, 2015). "In summary, ZNF671, an epigenetically silenced novel tumor suppressor, represents a potential predictor for UC relapse and non-invasive biomarker that could assist in UC clinical decision-making." (PMID 26320192, 2015). "To assess the possibility that ZNF671 tumor suppressive activity might relate to disruption of cancer “stemness” or EMT phenotypes, we examined the effects of ZNF671 on the expression of CSC markers." (PMID 26320192, 2015). "Further study of the role of KAP1 in the tumor suppressive function of ZNF671, however, is needed." (PMID 26320192, 2015). "Furthermore, in vivo experiments confirmed that overexpression of ZNF671 could inhibit tumor volume and weight, and down-regulate the expression of MAPK6." (PMID 37215982, 2023). "Previous studies showed that ZNF671 could act as a tumor suppressor in several solid tumors." (PMID 31781507, 2019). "However, the mechanism of ZNF671's tumor suppressor role remains unknown, and further studies are needed to clarify this issue." (PMID 31781507, 2019). "Functional analysis identified that ZNF671 might play a tumor suppressor role in cancer." (PMID 31781507, 2019). "Having demonstrated that the potential tumor suppressor ZNF671 is epigenetically silenced in UC, and in consideration of other cancer biomarkers found in human urine, we assessed the feasibility of using ZNF671 methylation as a biomarker for non-invasive cancer detection in urine." (PMID 26320192, 2015). "Moreover, ZNF671 methylation was significantly higher in tumor tissues, as compared to their adjacent normal tissues, and also significantly correlated with higher tumor grade and tumor relapse, in addition to associating with shortened locoregional disease-free survival." (PMID 26320192, 2015). "The results showed that the promoter methylation levels of ZNF671 and ZNF132 were significantly higher in CRC tumor tissues compared to normal mucosa." (PMID 40791581, 2025). "Analyzing the methylation levels of ZNF132 and ZNF671 and their impact on gene expression in CRC patient samples helps clarify the roles of these biomarkers in tumor development and progression." (PMID 40791581, 2025). "Gene enrichment analysis of tumor samples with high ZNF132 and ZNF671 methylation revealed their involvement in immune pathways and cell proliferation, highlighting their biological functions and potential prognostic value." (PMID 40791581, 2025). "Further analysis using WGCNA and xCell to explore the correlation between ZNF132 and ZNF671 expression and immune cell infiltration in the TME indicated that both genes are involved in regulating immune responses and tumor-stroma interactions." (PMID 40791581, 2025). "The enriched pathways included signal transduction, cell adhesion, immune regulation, metabolism, and disease development, underscoring the roles of ZNF671 and ZNF132 in tumor progression and prognosis." (PMID 40791581, 2025). "AMC-HN-8 and TU177 cells overexpressing or knockdown ZNF671 were subcutaneously injected into BALB/c nude mice, and the tumor volume and weight were measured." (PMID 37215982, 2023). "However, the contribution of tumor heterogeneity to the functional role of ZNF671 remains unknown." (PMID 31781507, 2019). "Of the promoters gaining methylation in our sample, many have already been shown to have tumour suppressor activity, including RORa, FAN1, PRDM1, CYGB, L3MBTL4, EPB41L3, with ZNF471 and ZNF671 being specifically silenced by methylation." (PMID 31357948, 2019). "The epigenetic silencing and tumor suppressive properties of ZNF671 is not confined to these cancers." (PMID 39595048, 2024).
tumor (continued). "Next we compared ZNF671 RNA transcript levels between primary tumor and matched adjacent non-tumor tissue for 30 of the same HNSCC patients using RNA sequencing data obtained from the TCGA." (PMID 39595048, 2024). "We also analyzed the expression level of ZNF671 in GSE59102 and GSE178218, and the results showed that the expression level of ZNF671 gene was significantly decreased, and the methylation level was significantly increased in the tumor group." (PMID 37215982, 2023). "For example, we did not investigate whether ZNF671 is related to other tumor characteristics, such as stem cell-like properties, epithelial-mesenchymal transition, etc." (PMID 37215982, 2023). "To date, our attempts to overexpress ZNF671 in other HNSCC cell lines, including SCC-15 and SCC-25, have not been successful, possibly due to its tumor suppressive properties." (PMID 39595048, 2024). "In this study, we confirmed that ZNF671 was epigenetically silenced and hypermethylated in a significant number of HNSCC primary tumor samples when compared to adjacent non-tumor samples from the same patient." (PMID 39595048, 2024). "Our analysis shows that both ZNF671 and IRF8 exhibited significantly lower gene expressions in BCa tumors than in non-BCa tissues, indicating potential tumor suppressive roles of the genes." (PMID 38472940, 2024). "ZNF671 expression is significantly correlated with the prognosis of LUAD, but its expression does not differ significantly between normal and tumor tissues." (PMID 37622116, 2023).
cancer (17 papers, 2014 to 2026). A tumor composed of atypical neoplastic, often pleomorphic cells that invade other tissues. "The present study found that downregulation of ZNF671 was associated with its promoter hypermethylation among many different cancer types." (PMID 31134149, 2019). "Overexpression of ZNF671 suppresses the expression of Notch1 and its downstream targets, whereas ZNF671 silencing enhances Notch pathway activation, promoting cancer cell proliferation and invasion—effects that can be reversed by Notch inhibition." (PMID 41602823, 2026). "Other real-time methylation-specific PCR analyses for the ZNF671 marker showed the highest detection rates for cervical scrapes with underlying CIN3 (67%) and cancer (90%)." (PMID 36803573, 2023). "We next explored the functional roles of ZNF671 in cancers, and analyzed the correlation between ZNF671 expression and functional state." (PMID 31781507, 2019). "The expression of ZNF671 and the activity of each functional state across single-cell datasets in different cancers were explored using an interactive bubble chart." (PMID 31781507, 2019). "We further evaluated the prognostic value of ZNF671 expression among numerous cancer types using the “Kaplan–Meier plotter” (KM plotter) database." (PMID 31134149, 2019). "We evaluated 14 functional states of ZNF671 in cancers and performed ZNF671 expression and function state correlation analysis." (PMID 31781507, 2019). "To determine the functionally heterogeneous roles of ZNF671 in cancer cells, we inferred that single cells exhibited widespread heterogeneity in terms of their functional states in cancer." (PMID 31781507, 2019). "We performed a pan-cancer analysis of the methylation status and mRNA and protein expression of ZNF671 using The Cancer Genome Atlas (TCGA) database and the Human Protein Atlas." (PMID 31134149, 2019). "Transwell assays showed that overexpression of ZNF671 inhibited cancer cell migration and invasion in vitro." (PMID 31781507, 2019). "The present study aimed to determine the functional states of ZNF671 in cancer single cells based on single-cell sequencing datasets (scRNA-seq)." (PMID 31781507, 2019). "To determine the methylation level of ZNF671 across cancer types, we analyzed human pan-cancer methylation data in the TCGA database." (PMID 31134149, 2019). "Our results provide new insights into the role of ZNF671 in multiple tumors and identifies ZNF671 as a novel target for cancer treatment." (PMID 31781507, 2019). "To reveal the roles of ZNF671 in different cell groups, we further the explored functional roles and correlations of ZNF671 in different cancer subgroups." (PMID 31781507, 2019). "To further explore the heterogeneous functional state of ZNF671 in cancers, we applied t-SNE to describe the distribution of cells." (PMID 31781507, 2019). "We further applied t-distributed stochastic neighbor embedding to describe the distribution of cancer cells and to explore the functional state of ZNF671 in cancer subgroups." (PMID 31781507, 2019). "Seven genes are hypermethylated in ten cancer sites: six encoding zinc finger transcription factors (ZNF135, ZNF354C, ZNF415, ZNF542, ZNF671, ZSCAN18) and one encoding a transmembrane protein (TMEM25)." (PMID 25631659, 2015). "While the sensitivity and specificity of cancer detection using ZNF671 methylation alone was 57.7% and 89.5%, combining hypermethylation of ZNF671 with that of IRF8 and SFRP1 increased the sensitivity to 96.2%." (PMID 26320192, 2015). "To further examine the predictive power of ZNF671 methylation for non-invasive cancer detection, we obtained another 61 urine samples (33 bladder UC and 28 non-cancer) as a test set for single-blind analysis." (PMID 26320192, 2015). "We therefore examined the sensitivity and specificity of cancer detection in urine by combining methylated ZNF671 with methylation of two other TSGs (IRF8 and sFRP1) using a previously published urine sample cohort (26 UCs and 19 non-cancerous controls)." (PMID 26320192, 2015).
cancer (continued). "As was the case for the tissues, qMSP analyses for the ZNF671 marker region showed the highest detection rates for cervical scrapes with underlying CIN3 (67%) and carcinoma (90%)." (PMID 24647315, 2014). "We suspect that ZNF671 represses transcription of key genes involved in cancer progression." (PMID 39595048, 2024). "Overall, elucidating the mechanism of ZNF671 action may provide us with new insights into a role for ZNF671 in cancer treatment." (PMID 39595048, 2024). "Finally, we shed some light on long non-coding RNA LINC00665 as a novel target for ZNF671, and its subsequent effect on multiple cancer-related signaling pathways." (PMID 39595048, 2024). "A total of eight cancer-related ZNF671 scRNA-seq datasets were included in the study." (PMID 31781507, 2019). "In this study, we analyzed the expression of ZNF671 in cancer scRNA-seq datasets systematically." (PMID 31781507, 2019). "We collected cancer-related ZNF671 scRNA-seq datasets and analyzed ZNF671 in the datasets." (PMID 31781507, 2019). "We found that ZNF671 was downregulated in eight cancer-related ZNF671 scRNA-seq datasets." (PMID 31781507, 2019). "The protein expression level of ZNF671 was downregulated in most cancers." (PMID 31134149, 2019). "Indeed, we observed enrichment of gene sets associated with cancer, including the mitotic spindle and G2/M checkpoint pathways, in ZNF671-high expressing tumors; conversely, these pathways were not enriched in ZNF671-low expressing tumors." (PMID 29052525, 2017). "Further analysis across various cancers showed that ZNF132 and ZNF671 expression was significantly correlated with immune cell infiltration." (PMID 40791581, 2025). "A panel of five DNA methylation markers (FER1L4, ZNF671, ST8SIA1, TBX15, and ARHGEF4) detected 74% of EC cancer patients with an overall specificity of 91%." (PMID 35242243, 2022). "To determine the functional roles of ZNF671 in cancer cells, we performed Western blot assay and migration and invasion assays using U87, U251, A375, MDA-MB-231, and BT-549 cell lines transfected with ZNF671 or vector plasmids." (PMID 31781507, 2019). "However, the roles of ZNF671 in the functional heterogeneity of cancer single cells remain unclear." (PMID 31781507, 2019). "The ZNF671 marker region showed the highest detection rates for both, CIN3 (40 of 43 samples; 93%) and carcinoma samples (52 of 54 samples; 96%)." (PMID 24647315, 2014). "ZNF671 methylation in cancer tissues was significantly higher than in adjacent non-cancerous tissues (P = 0.0001)." (PMID 26320192, 2015). "In contrast to HUC cells, ZNF671 was down-regulated in some, but not all of those non-UC cancer cell lines." (PMID 26320192, 2015). "For early-stage cancers, DNA methylation-based biomarkers are of particular importance Recent scientific work indicates the high potential of hypermethylated genes TWIST1, VIM, ZNF671, OTX1, and IRF8 for early diagnosis and PTK2, AHNAK, and DAPK for BC prognosis." (PMID 39685620, 2024). "However, there is limited information regarding the role of ZNF671 in cancer progression and development, and there have been no systematic studies of the role of ZNF671 in cancer's heterogeneous functional states." (PMID 31781507, 2019). "Moreover, further analysis showed that ZNF671 methylation was significantly elevated in high-grade, but not low-grade, cancer tissues (P = 0.003)." (PMID 26320192, 2015). "Statistical analysis indicated that ZNF671 expression was low and/or absent in urothelial (75%), breast (90.9%), cervical (90%), endometrial (83.3%), head and neck (100%), renal (100%), liver (77.8%), lung (100%), pancreatic (72.7%), prostate (100%), skin (100%), and thyroid (75%) cancers." (PMID 31134149, 2019).
ZNF671 also shares sentences with these, for which no sentence is quoted: melanoma (4 papers); pancreatic adenocarcinoma (3); breast invasive carcinoma (2); endocervical adenocarcinoma (2); lung adenocarcinoma (2); uterine corpus endometrial carcinoma (2); clear cell renal cell carcinomas (1); gestational choriocarcinoma (1); glioma (1); head and neck squamous cell carcinoma (1); laryngeal carcinoma (1); oropharyngeal cancer (1); stomach cancers (1); thyroid cancer (1).